CD38 (CD38 molecule)
Diseases named in the same sentence as CD38 in open-access papers (continued):
Sharing a sentence is not in itself a finding about the gene and the disease.
multiple myeloma (continued). "Anti-CD38 CAR-T cells are effective in eliminating primary myeloma cells as well as myeloma cell lines." (PMID 38783333, 2024). "CD38 is a surface ectoenzyme expressed at high levels on myeloma plasma cells and is the target for the monoclonal antibodies (mAbs) daratumumab and isatuximab." (PMID 40453054, 2024). "For example, “Daratumumab” is an FDA-approved anti-CD38 monoclonal antibody for the treatment of multiple myeloma." (PMID 38912057, 2024). "On the other hand, CD38 is mainly regarded as the biomarker of the Plasma Blast-Plasma cell, particularly highly and uniformly expressed in Multiple Myeloma, a cancer characterized by proliferation of malignant plasma cells in the bone marrow." (PMID 38307922, 2024). "Daratumumab and isatuximab, both targeting the CD38, are approved therapies for multiple myeloma, yet they exhibit distinct mechanistic profiles." (PMID 38765013, 2024). "Currently, the U.S. Food and Drug Administration approved the monoclonal antibody, daratumumab, against CD38 for managing multiple myeloma, and a few other CD38 blocking antibodies are in clinical trials." (PMID 39180173, 2024). "Isatuximab, an immunoglobulin (Ig) G1 monoclonal antibody, targets a specific epitope of human CD38, inducing myeloma cell death through multiple mechanisms." (PMID 38830994, 2024). "The used mathematical model does not account for the heterogeneity of receptor expression within the cancer cell population, and we are unaware of literature data quantitatively addressing the heterogeneity of CD38 expression in multiple myeloma lesions." (PMID 39466073, 2024). "The anti-myeloma effect of untreated amplified NK cells was limited compared with that of CD38−/low NK cells." (PMID 38410372, 2024). "We then correlated expression (via Pearson R) of these transcription factors with CD38 expression across 664 primary patient tumors at diagnosis in the Multiple Myeloma Research Foundation CoMMpass database (release IA13)." (PMID 40453054, 2024). "Targeted immunotherapy combinations, including the anti-CD38 monoclonal antibody (MoAb) daratumumab, have shown promising results in patients with relapsed/refractory multiple myeloma (RRMM), leading to a considerable increase in progression-free survival." (PMID 39030183, 2024). "Most CD38 inhibitors are antibodies, such as Darzalex (daratumumab), which has been approved by the US Food and Drug Administration to treat multiple myeloma patients." (PMID 38129670, 2024). "It targets CD38, a transmembrane glycoprotein that is highly expressed on multiple myeloma cells and other immune cells." (PMID 39065666, 2024). "We therefore performed a retrospective analysis of patients followed for multiple myeloma in our tertiary center and who had died over the past five years in the era of CD-38 targeted therapies." (PMID 39544298, 2024). "Early non-clinical and initial human data from studies involving patients with multiple myeloma have shown mezagitamab to have a favorable safety profile and promising pharmacodynamic effects, particularly in the reduction of CD38-expressing target cells." (PMID 39472388, 2024). "Next, we collected bone marrow samples from 5 cases of multiple myeloma, and found that higher level of LILRB4 in CD45−/CD38+ multiple myeloma cells seems to correspond to a tendency towards more RELT level in serum." (PMID 38951916, 2024). "Nanocarriers can be designed to recognize and bind to specific molecular markers on myeloma cells, such as CD38, CD138, and BCMA, ensuring the targeted delivery of immunotherapeutic agents." (PMID 38254683, 2024). "A second mAb targeting CD38, isatuximab, was also recently approved for relapsed/refractory myeloma; at least 15 additional CD38-targeting agents are in development." (PMID 40453054, 2024). "Daratumumab (dara), a monoclonal antibody (mAb) that targets CD38 results in antibody-dependent cellular cytotoxicity (ADCC) of both multiple myeloma (MM) cells and NK cells." (PMID 38515757, 2024).
multiple myeloma (continued). "NK cells are crucial mediators of ADCC against myeloma cells by mAb therapy targeting CD38, CS1, and BCMA in multiple myeloma." (PMID 38284882, 2024). "In multiple myeloma, CD38‐targeting mAbs, such as daratumumab (DARA), have been approved for treatment." (PMID 39364393, 2024). "Isatuximab, an anti-CD38 antibody, has been widely used in treatments for patients with relapsed/refractory multiple myeloma (MM)." (PMID 38758239, 2024). "In multiple myeloma (MM), CD38 is an important target for monoclonal antibody therapy because MM plasma cells have increased CD38 expression compared with that in normal cells." (PMID 38983860, 2024). "Taken together, these results nominate XBP1 as a particularly strong determinant of surface CD38 in myeloma plasma cells, although future investigation will be required to validate a direct or indirect relationship to CD38 transcription." (PMID 40453054, 2024). "The role of combination CD38 blockade with anti-PD1 therapy has been explored in the treatment of multiple myeloma and in a phase I/II study of metastatic castrate-resistant prostate cancer and NSCLC." (PMID 39207194, 2024). "Recently, epigenetic drugs such as DNA methyltransferase inhibitors (DNMTis) and histone deacetylase inhibitors (HDACis) were shown to upregulate CD38 expression, thus augmenting the anti-myeloma effect of daratumumab." (PMID 38731936, 2024). "These antigens include CD74, CD20, CCR7, and CD25 for lymphomas; CD71, CD123, CD25, and CD38 for leukemias; and CD38 for myeloma and light chain amyloidosis." (PMID 39545074, 2024). "One such agent, SAR442257, is a trispecific TCE that binds CD38 on multiple myeloma cells, CD3 on T cells and CD28, which is expressed on T cells and some multiple myeloma cells." (PMID 38421887, 2024). "Daratumumab is a humanized anti-CD38 monoclonal antibody used to treat multiple myeloma and has been reported to treat R/R-AL safely and effectively." (PMID 39046511, 2024). "In detail, several immunotherapeutic approaches targeting CD38 on myeloma cells have been proven to significantly improve patient survival." (PMID 38610989, 2024). "Gene-edited NK cells with CD3−/low CD16F158V and CD38KO-NK cells can target and eliminate CD38−/low myeloma cells." (PMID 38410372, 2024). "Anti-CD38 monoclonal antibodies like Daratumumab (Dara) are effective in multiple myeloma (MM); however, drug resistance ultimately occurs and the mechanisms behind this are poorly understood." (PMID 38355622, 2024). "High ex vivo response rates were observed in primary aspirates taken from patients with multiple myeloma at diagnosis, with modestly reduced response in multiple myeloma recently treated with anti-CD38 mAbs." (PMID 38421887, 2024). "In summary, our data show that tinostamustine increases the expression of CD38 as well as ligands for NKG2D in myeloma cells." (PMID 38731936, 2024). "Daratumumab is a CD38-targeting antibody that is being increasingly integrated into first-line multiple myeloma (MM) induction treatment, leading to an improved response depth and a longer progression-free survival." (PMID 38791933, 2024). "For instance, exclusion of patients with smoldering MM or primary amyloidosis and those with prior anti-CD38 therapies or stem cell transplantation, limits broader applicability." (PMID 38182614, 2024). "Anti-CD38 monoclonal antibody (MoAB) therapy has significantly improved the prognosis of patients with multiple myeloma." (PMID 37763245, 2023). "Daratumumab is the first human-specific anti-CD38 IgG1 monoclonal antibody approved for the treatment of multiple myeloma." (PMID 37373995, 2023). "Similar reduction was observed in multiple myeloma (MM) upon TNT disruption by cytochalasin D as well as after blocking of CD38, a surface glycoprotein that stimulates TNT formation." (PMID 36795453, 2023). "They assessed refractoriness to the three main classes of anti-myeloma drugs (PI, IMiDs, and Anti-CD38)." (PMID 37296856, 2023).
multiple myeloma (continued). "Despite continuous improvement in survival, patients with multiple myeloma (MM) still relapse, and survival after failure of proteasome inhibitor (PIs), immunomodulatory drugs (IMiDs), and anti-CD38 monoclonal antibodies remains poor." (PMID 37511588, 2023). "A target sink effect has been reported in daratumumab, a CD38 monoclonal antibody, due to the abundant expression of CD38 in myeloma." (PMID 37634013, 2023). "In recent years, different groups have assessed the utility of myeloma-specific agents targeted to myeloma proteins such as CD38 and CXCR4." (PMID 36008121, 2023). "The findings of this study underscore the indispensable nature of CD38 deletion in realizing the therapeutic potential of anti-CD38 CAR-expressing NK cells for the treatment of multiple myeloma." (PMID 38139060, 2023). "Despite the high percentage of patients in Kd who received anti-CD38 in further anti-myeloma therapy, benefit with Isa-Kd over Kd was maintained late through PFS2 with a HR of 0.68 (95% CI: 0.50–0.94)." (PMID 37156782, 2023). "In a multi-dose phase 1 clinical trial, FT538 was used for the treatment of AML, in combination with daratumumab, a CD38-targeted monoclonal antibody therapy used for the treatment of multiple myeloma (NCT04614636)." (PMID 36830717, 2023). "More recent improvements in anti-myeloma therapeutic regimens include the monoclonal antibody Daratumumab (targeting CD-38) and chimeric antigen receptor or CAR-T-cell therapy." (PMID 38057320, 2023). "ATRA treatment has been shown to increase the CD38 expression in multiple myeloma, where it helps in mitochondrial transfer from BM-MSCs to myeloma cells." (PMID 38169927, 2023). "Teclistimab targets CD3 (expressed on the T-cell surface) and BCMA (expressed on the myeloma cell surface) and is now given for those with refractory or relapsed MM with prior exposure to triple therapy (IMiD, PI, and anti-CD38)." (PMID 38009096, 2023). "In clinical practice, CD38-targeted therapy using CD38 monoclonal antibodies has been performed in patients with hematologic malignancies such as multiple myeloma (MM), which highly expresses CD38 on their malignant cells." (PMID 36831262, 2023). "Studies have shown that CD38 is highly and uniformly expressed at the cell surface of multiple myeloma (MM) cells, and monoclonal antibodies against CD38 are highly efficacious in the treatment of MM." (PMID 37834375, 2023). "CD38 has been established as an important therapeutic target for multiple myeloma (MM), for which two CD38 antibodies are currently approved—daratumumab and isatuximab." (PMID 37840445, 2023). "Targets expressed in all myeloma patients show high inter-patient variation, e.g., 6.8 (CD38), 6.9 (BCMA), 9.9 (GPRC5D), and 10.9 (FCRH5) log-fold variation." (PMID 38035078, 2023). "Antibodies that target CD38, a glycoprotein that is uniformly expressed on myeloma cells and plays important roles in immune‐system evasion, are increasingly incorporated into earlier lines of treatment for MM." (PMID 36866838, 2023). "Daratumumab and isatuximab bind to CD38, a cell surface receptor highly expressed in myeloma cells and several types of immune cells, and exert their action through Fc-dependent mechanisms and immunomodulatory effects." (PMID 36944635, 2023). "In pre-clinical studies, this agent induced irreversible ribosome inactivation and potent cytotoxicity against CD38-positive human myeloma models." (PMID 37111346, 2023). "Intriguing combination therapies demonstrated that blockade of the myeloid checkpoint CD38 by daratumumab, a therapeutic Ab approved for multiple myeloma, invigorated the killing of acute lymphoblastic T-cell leukemia cells in vitro." (PMID 37686465, 2023). "The lethality of anti-CD38 antibodies to myeloma cells is due to a combination of antibody-dependent cellular cytotoxicity (ADCC), antibody-dependent cellular phagocytosis (ADCP), and complement-dependent cytotoxicity (CDC)." (PMID 37958658, 2023).
multiple myeloma (continued). "Daratumumab and isatuximab are two CD38 targeting antibodies approved for the treatment of multiple myeloma." (PMID 37840445, 2023). "Patients who are refractory to three classes of anti-myeloma drugs including at least one PI, one IMiD, and one anti-CD38 monoclonal antibody have poor prognosis with an estimated median OS less than a year." (PMID 37511588, 2023). "Considering how rapidly the treatment of MM is evolving, soon, with the introduction of quadruplet regimens for newly diagnosed myeloma, most patients will be exposed in their earlier lines of therapy to PIs, IMiDs, and CD38 monoclonal antibodies." (PMID 37296856, 2023). "Given the incurable nature of multiple myeloma (MM), efforts are made to improve the efficacy of anti‐CD38 monoclonal antibodies via combinations with other potentially synergistic therapies." (PMID 36866838, 2023). "Using the filtering algorithms established with cell line studies, 103 candidate rearrangements with corresponding CDR3 sequences were identified in 29 CD38+ CD138+ flow cytometry-sorted bone marrow samples with active myeloma." (PMID 36328595, 2023). "Recently, monoclonal antibodies directed against surface antigens, such as daratumumab (anti-CD38), have been tested and finally approved in the treatment of myeloma." (PMID 37509726, 2023). "Plasma cells from patients with myeloma showed minimal cell division in either model, but the cells retained their original immunophenotype (CD38+, CD319+, and CD56+) more consistently in the organoids than in the 3D BM-MSC." (PMID 36351055, 2023). "The CD38 protein is a prognostic marker of chronic lymphocytic leukemia and a therapeutic target in multiple myeloma, and has an established role as an immunomodulator in cancer." (PMID 37415732, 2023). "The anti-CD38 monoclonal antibody isatuximab (Isa) exerts anti-myeloma activity through several mechanisms of action including antibody-dependent cell-mediated cytotoxicity, complement-dependent cytotoxicity, and direct induction of apoptotic cell death." (PMID 37156782, 2023). "Most studies used rituximab (anti-CD20) to potentiate the NK cell response against B cell leukemias, in neuroblastoma ADCC can be triggered with anti-GD2, while in multiple myeloma daratumumab (anti-CD38) was used." (PMID 36261539, 2023). "Patients progressing after CD38 MoAB-based therapies are also frequently resistant to other commonly used anti-myeloma agents such as lenalidomide and bortezomib." (PMID 37763245, 2023). "CD38 is an ectoenzyme ubiquitously expressed on the surface of various hematologic cells, including multiple myeloma (MM)." (PMID 38139060, 2023). "ICAM-1 conjugated with a cytotoxic drug was extensively tested for multiple myeloma and another bispecific anti-CD38-ICAM-1 drug for multiple myeloma is under development." (PMID 37006265, 2023). "Daratumumab, an anti-CD38 monoclonal antibody common in myeloma treatment, has also proven to increase platelet transfusion efficiency in refractory patients." (PMID 36845153, 2023). "Isatuximab (Sarclisa®) is an immunoglobulin (Ig)G1 monoclonal antibody (mAb) that targets a specific epitope of CD38 and contributes to myeloma cell killing via multiple mechanisms of action." (PMID 36866838, 2023). "A notable example is multiple myeloma, where the anti-CD38 daratumumab has become a cornerstone in current induction regimens." (PMID 38201614, 2023). "Primary multiple myeloma cells were costained for CD38, confirming that cells derived from the malignant plasma cell clone had successfully engrafted." (PMID 36351055, 2023). "The phase 3 clinical trial (NCT03617731) succeeded in testing combinations of blocking Abs against CD38 on plasma cells (isatuximab) with global protein-degrading agents (lenalidomide, bortezomib) and dexamethasone in patients with multiple myeloma." (PMID 37686465, 2023).
multiple myeloma (continued). "The CD38 antigen represents a frequently expressed antigen on plasma cells, which makes them an excellent target for treatment in multiple myeloma (MM) by anti-CD38-directed agents." (PMID 37374055, 2023). "As a consequence, there is increasing interest in combinatorial immunologically based strategies that employ BCMA with other validated myeloma targets, such as CD38, SLAMF7, and CD19 or with emerging viable targets like GPRC5D." (PMID 37958658, 2023). "The buffy coat layer includes bone marrow stromal cells which support survival of the cocultured multiple myeloma cells (identified as CD38+/CD45lo) ex vivo." (PMID 37956312, 2023). "The introduction of immunomodulatory drugs, proteasome inhibitors and anti-CD38 monoclonal antibodies has transformed the treatment landscape in multiple myeloma." (PMID 37582952, 2023). "Recently in clinical trials, CD38-specific human monoclonal antibodies have been successfully used to treat patients with multiple myeloma (MM), suggesting CD38 is a viable target for therapy." (PMID 37735675, 2023). "Preclinical investigations demonstrating anti-CD38 CAR-T-cell therapy’s anti-myeloma potential have catalyzed numerous clinical trial commencements." (PMID 38006053, 2023). "DNA hypomethylation enhances the expression of CD38 in multiple myeloma and NGAL-R in esophageal squamous cell carcinoma." (PMID 37760777, 2023). "The characterization of the CD38 protein and its overexpression on myeloma cells has resulted in the development of monoclonal antibodies (mAbs) targeting CD38, of which two antibodies—daratumumab and isatuximab—have been approved for clinical use." (PMID 37840445, 2023). "Our rationale stems from the design of our CAR, which exhibits a heightened sensitivity, enabling it to identify myeloma cells expressing low levels of CD38, a phenomenon frequently observed in relapsed patients." (PMID 38139060, 2023). "So far, the majority of CD38 CAR T-cell treatments are designed to treat multiple myeloma (MM); however, favorable safety data will allow for the segue into other hematological malignancies that are CD38+." (PMID 38817957, 2023). "Based on the highly expressed antigens on the surface of myeloma cells, the targets of MM nanomedicines mainly include CD38, folate receptor (FR) and VLA4." (PMID 37353849, 2023). "Adult patients with relapsed or refractory multiple myeloma who have received at least four prior lines of therapy, including a proteasome inhibitor, an immunomodulatory agent, and an anti-CD38 monoclonal antibody." (PMID 37304291, 2023). "The original authorization was applicable for those myeloma patients who have received at least four prior therapies including an anti-CD38 monoclonal antibody, a proteasome inhibitor, and an immunomodulatory drug." (PMID 36982377, 2023). "This multi-center retrospective cohort study used the Canadian Myeloma Research Group Database to describe real-world outcomes of patients withanti-CD38 monoclonal antibody (mAb) refractory MM subsequently treated with standard of care (SoC) regimens." (PMID 38065967, 2023). "Daratumumab, an anti-CD38 monoclonal antibody with proven efficacy in MM or AL amyloidosis, is of particular interest." (PMID 37120733, 2023). "This antibody showed in first proof-of-concept studies potent anti-myeloma activity comparable to the clinically approved CD38 IgG1 antibodies daratumumab and isatuximab used for MM immunotherapy." (PMID 35784366, 2022). "CD38 is abundantly expressed in multiple myeloma (MM) and some non-Hodgkin’s lymphomas (NHLs), and is emerging as a new therapeutic target for these diseases." (PMID 36313735, 2022). "There is now substantial evidence for the additional benefit of anti‐CD38 monoclonal antibody treatment when added to anti‐myeloma therapy from multiple trials in the frontline (MAIA, CASSIOPEIA, GRIFFIN) and relapsed settings (CASTOR and POLLUX)." (PMID 36051015, 2022).